GPR151 (G protein-coupled receptor 151)
Description:
Proton-sensing G protein-coupled receptor.
Synonyms: GalRL; GALR4; PGR7; GPCR; GPCR-2037
Tractability: Small molecule: it belongs to a druggable protein family. Antibody: UniProt places it where antibodies can reach, with high confidence; UniProt predicts a signal peptide or a membrane-spanning region; its Gene Ontology location is reachable by antibodies, with medium confidence.
Target class: Family A G protein-coupled receptor; Membrane receptor
Gene: Protein-coding gene on chromosome 5 (146,513,144 to 146,516,190, reverse strand). Ensembl gene ENSG00000173250.
Subcellular location: Cell membrane
Gene Ontology:
Molecular function: G protein-coupled receptor activity; identical protein binding; protein binding
Biological process: G protein-coupled receptor signaling pathway; response to acidic pH; positive regulation of immune response; response to ischemia; regulation of synaptic vesicle exocytosis
Cellular component: plasma membrane; cholinergic synapse; membrane; presynaptic membrane; synaptic vesicle membrane
Genetic constraint (gnomAD): Loss-of-function variants: 21 observed, 26.35 expected, observed/expected ratio (o/e) 0.8, 90% interval 0.56 to 1.15. The upper end of that interval is the gene's LOEUF score, 1.15, which puts it in group 5 of 6, group 1 being the genes least tolerant of losing a copy. Missense variants: 508 observed, 531.05 expected, observed/expected ratio (o/e) 0.96, 90% interval 0.89 to 1.03. Synonymous variants: 202 observed, 202.03 expected, observed/expected ratio (o/e) 1, 90% interval 0.89 to 1.12.
Homologues: Orthologues: chimpanzee GPR151 (99% identical), macaque GPR151 (97% identical), dog GPR151 (83% identical), rabbit GPR151 (82% identical), pig GPR151 (79% identical), guinea pig GPR151 (78% identical), rat Gpr151 (78% identical), mouse Gpr151 (77% identical), tropical clawed frog gpr151 (51% identical), zebrafish GPR151 (43% identical). Paralogues in human: RXFP3 (18% identical), GPR174 (12% identical), P2RY11 (12% identical), GPR183 (12% identical), GPR132 (11% identical), GPR146 (11% identical), GPR141 (10% identical).
Diseases named in the same sentence as GPR151 in open-access papers:
GPR151 is named in the same sentence as 33 diseases in open-access papers, as found by Europe PMC text mining. Sharing a sentence is not in itself a finding about the gene and the disease. The quoted sentences say what the papers report.
Obesity (8 papers, 2018 to 2025). Accumulation of substantial excess body fat. "pLOF variants in the gene GPR151 protect against obesity and type 2 diabetes, in the gene IL33 against asthma and allergic disease, and in the gene IFIH1 against hypothyroidism." (PMID 29691411, 2018). "Whole-body loss of Gpr151 confers increased glucose tolerance in high-fat diet-induced obesity." (PMID 36456565, 2022). "As the LOF GPR151 variant was associated with lower BMI in humans, we compared body weights of Gpr151 wild-type (WT) and knockout littermates fed either standard diet (SD) or obesity-inducing high-fat diet (HFD)." (PMID 36456565, 2022). "Furthermore, we show that GPR151 has a cell-autonomous role in hepatic gluconeogenesis and that loss of Gpr151 is protective for metabolic health in diet-induced obesity through decreasing gluconeogenesis in hepatocytes." (PMID 36456565, 2022). "In this study, we identified pLOF variants that protect against obesity (GPR151), asthma (GSDMB, IL33), autoimmune disorders (IFIH1), and coronary artery disease (PDE3B), prioritizing genes and pathways for which pharmacologic attempts to mimic these protective mutations might ameliorate disease." (PMID 29691411, 2018). "Recent publications reported associations between loss of GPR151 function and low body mass index (BMI), raising the possibility of inhibiting GPR151 for the treatment of obesity and metabolic syndromes." (PMID 35381001, 2022). "Given the association between GPR151 LOF variant p.Arg95Ter and lower odds ratio for T2D, obesity and reduced BMI, we examined the function of GPR151 with respect to metabolic health in diet-induced obesity (DIO)." (PMID 36456565, 2022). "For obesity and type 2 diabetes, these results hightlight GPR151 as a potential therapeutic target." (PMID 29691411, 2018). "In summary, Gpr151 loss impairs hepatic glucogenesis regardless of the presence of glucagon, which likely explains its effects on whole-body glucose metabolism in diet-induced obesity." (PMID 36456565, 2022). "We observe that GPR151 loss does not affect BMI to a clinically relevant extent and conclude that inhibiting GPR151 may not be effective at treating obesity." (PMID 35381001, 2022). "Transcripts for several candidate genes for obesity were absent in the whole brain or absent in specific regions of the brain (Cyp17a1, Gdf15, Gpr151, Lmx1b, Olig3, Sbk1, Sim1, Skor1, Tnni3k)." (PMID 39920851, 2025). "Together, our findings indicate that GPR151 antagonism is not a compelling therapeutic approach to treatment of obesity." (PMID 35381001, 2022).
Anxiety (3 papers, 2019 to 2022). Intense feelings of nervousness, tension, or panic often arise in response to interpersonal stresses. "Subsequently, we analyzed the anxiety response using the novel tank test and expression of galr2a/2b and serotonin-related genes using quantitative RT-PCR in Tg(gpr151:gal4vp16);Tg(5xuas:spx1:p2a-mCherry) zebrafish." (PMID 31474838, 2019). "Further, the latency to first entry in the social compartment was not impaired in B4MOR and GPR151 null mutants, suggesting altogether that mutant mice are not less sociable because of higher anxiety." (PMID 36424418, 2022). "There is an anxiety-like behavioral phenotype in mice lacking the GPR151 expressing neurons." (PMID 33589739, 2022).
type 2 diabetes (3 papers, 2018 to 2022). "Recently a rare, putative loss-of-function mutation in the orphan G-protein coupled receptor 151 (GPR151) was found to be associated with lower odds ratio for type 2 diabetes, but the mechanism behind this association has remained elusive." (PMID 36456565, 2022). "Rare variants in the G-protein coupled receptor 151 (GPR151) gene in humans are associated with lower odds ratio for type 2 diabetes, but the mechanism behind this association has remained elusive." (PMID 36456565, 2022). "In this work, we establish a previously unknown role of Gpr151 in the liver that provides an explanation to the lowered type 2 diabetes risk in individuals with nonsynonymous mutations in GPR151." (PMID 36456565, 2022).
squamous cell carcinoma (2 papers, 2021 to 2023). A carcinoma arising from squamous epithelial cells. "In this study, we investigated the expression profiles of TASK1, TASK3, GPR31 and GPR151 in squamous cell carcinomas (SCCs), basal cell carcinomas (BCCs), nevus cell nevi (NCN), and malignant melanomas (MMs)." (PMID 35011589, 2021). "They observed highly expressed GPR151 levels in squamous cell carcinomas." (PMID 36902589, 2023).
colorectal carcinoma (1 paper, 2023). A malignant epithelial neoplasm that arises from the colon or rectum and invades through the muscularis mucosa into the submucosa. "Since the expression of GPR151 was very strong in all of our immunohistochemical stainings, GPR151 seems to play a mandatory role in the formation and development of a peritoneal carcinomatosis of the colorectal carcinoma." (PMID 36902589, 2023).
neuroblastoma (1 paper, 2017). Neuroblastoma (NB) is the most common solid, extracranial childhood tumor. "ND7/23 cells (a hybridoma of mouse neuroblastoma and rat DRG) were transiently transfected with Gpr151, and calcium signalling measured using the calcium indicator Fluo-4." (PMID 27913310, 2017).
nicotine addiction (1 paper, 2023). "Another potential target is GPR151, an orphan GPCR expressed in the medial habenula that previously showed promise as a target for treating nicotine addiction." (PMID 37599003, 2023).
schizophrenia (1 paper, 2026). A major psychotic disorder characterized by abnormalities in the perception or expression of reality. "Comparison of these differentially expressed genes with a curated list of schizophrenia-associated genes revealed that the overlapping 217 genes, as well as the ANO1 and GPR151 genes, exhibited marked differences in expression patterns in ANO1 cKO mice." (PMID 41527097, 2026).
Simpson-Golabi-Behmel syndrome (1 paper, 2019). Simpson-Golabi-Behmel syndrome is a rare X-linked multiple congenital anomalies syndrome, characterized by pre- and postnatal overgrowth, distinctive craniofacial features, variable congenital malformations, organomegaly and an increased tumor risk. "Specifically, the expression and function of PDE3B and GPR151 were evaluated in mouse 3T3-L1 and human Simpson-Golabi-Behmel Syndrome (SGBS) cells, two well-established preadipocyte models used for studying adipocyte differentiation (i.e. adipogenesis) and function." (PMID 31492854, 2019).
skin cancer (1 paper, 2021). "We examined the expression profiles of GPR31, GPR151, TASK1 and TASK3 in the most common types of skin cancer." (PMID 35011589, 2021).
substance dependence (1 paper, 2025). The psychological or physiological need to take a substance in order to experience its effects or to avoid the effects of its absence. "Given its proposed inhibitory function,modulating GPR151 couldoffer a novel strategy for dampening maladaptive neural activity,potentially mitigating chronic pain, substance dependence, and neuropsychiatricdisorders." (PMID 40295925, 2025).
trigeminal neuralgia (1 paper, 2023). Trigeminal neuralgia is a nerve disorder that causes a stabbing or electric-shock-like pain in parts of the face. "Therefore, GPR151 may be a potential drug target for treating trigeminal neuralgia." (PMID 37264427, 2023).
metabolic disease (2 papers, 2021 to 2023). A congenital disorder (due to inherited enzyme abnormality) or acquired (due to failure of a metabolically important organ) disorder resulting from an abnormal metabolic process. "GPR151 is abundantly expressed in the dorsal root ganglia and is closely associated with nociception, making it a potential drug target for treating a variety of psychiatric, neurological, and metabolic disorders." (PMID 37296398, 2023).
tumor (2 papers, 2021 to 2023). "Studies on cBioportal were analyzed for mutation frequencies of GPR31, GPR151, KCNK3, and KCNK9 in the investigated tumor entities." (PMID 35011589, 2021). "In contrast to these tumor entities, BCCs were negative in ~50% of the samples, which is a striking immunohistochemical feature and similar to the results we found for GPR31, GPR151, TASK1, TASK3 and ASIC2." (PMID 36674553, 2023).
brain disease (1 paper, 2022). "GPR151 is an orphan GPCR densely and almost exclusively expressed in the habenular pathway, and this highly restricted expression pattern in the brain makes this particular GPCR a highly valuable potential target for brain disease." (PMID 36424418, 2022).
cancer (1 paper, 2025). A tumor composed of atypical neoplastic, often pleomorphic cells that invade other tissues. "As GPR151 is shown tobe acid-sensitive, a few studies investigatedwhether this protein is implicated in various cancers, as acidic environmentscan be generated by tumor metabolic changes and altered membrane-boundtransporters." (PMID 40295925, 2025). "One potential explanation for the upregulationof GPR151 in cancer cells is the fact that cancer is often comorbidwith chronic pain." (PMID 40295925, 2025).
GPR151 also shares sentences with these, for which no sentence is quoted: allergic disease (1 paper); asthma (1); autoimmune disorders (1); basal cell carcinoma (1); central obesity (1); colon cancer (1); coronary artery disease (1); depression (1); diabetes (1); genetic disease (1); hypothyroidism (1); injury (1); malignant melanomas (1); metabolic syndrome (1); Pain (1); Prader-Willi syndrome (1); Skin Tumors (1).